KRAS (KRas proto-oncogene, GTPase)
Diseases named in the same sentence as KRAS in open-access papers (continued):
Sharing a sentence is not in itself a finding about the gene and the disease.
gallbladder cancer (28 papers, 2010 to 2026). "Distal cholangiocarcinoma (dCCA), arising from the extrahepatic bile duct (ductus choledochus), and gallbladder carcinoma show overlapping molecular features, including KRAS mutations, ERBB2 amplification, BRCA1/2 alterations, and MSI-H in a minority of cases." (PMID 41535645, 2026). "Moreover, KRAS mutation is one of the most common genomic alternations in gallbladder cancer, and KRAS-associated genes were upregulated in GBC cell lines compared with L-2F7." (PMID 36387215, 2022). "To determine the significance of EGFR and ERBB2 constitutive phosphorylation and KRAS mutant alleles in gallbladder cancer cells, we set out to establish whether expression of ERBB2 is required for gallbladder tumor cell survival." (PMID 30304546, 2019). "Another possible explanation could involve the higher rate of KRAS mutations seen in intrahepatic cholangiocarcinomas as compared with gallbladder cancers, possibly mediating resistance to upstream HER2 blockade." (PMID 26022204, 2015). "KRAS mutations drive MAPK pathway activation and are considerably more frequent in eCCA and gallbladder carcinoma than in iCCA, with KRAS p.G12C representing only a small fraction of these alterations." (PMID 41535645, 2026). "In contrast, pCCA and dCCA, as well as gallbladder carcinoma, more commonly exhibit KRAS-alterations and ERBB2-/HER2 amplification/overexpression." (PMID 41535645, 2026). "While FGFR2 fusions are commonly found in ICC, KRAS mutations are frequent in ECC and gallbladder cancer and significantly associated with poor prognosis." (PMID 33921232, 2021). "By sponging miR-206, MALAT1 up-regulates ANXA2 and KRAS expression in gallbladder cancer cells, and reduces CDC42 and up-regulates CDK4 expression in breast cancer cells." (PMID 32174966, 2020). "By functioning as a ceRNA for miR-206, MALAT1 up-regulates the expression of the oncogenic ANXA2 and KRAS, and promotes gallbladder cancer cell proliferation and invasion in vitro and tumor progression in mice." (PMID 32174966, 2020). "In contrast, recent studies showed that the frequency of KRAS mutations is <20% in PBM-associated gallbladder cancer, which is comparable to that in non-PBM-associated gallbladder cancer." (PMID 35204432, 2022). "In patients, KRAS mutations were detected more frequently in pCCA (40%, 4/10) and dCCA (44.4%, 4/9) than in iCCA (5.9%, 2/34), while none was found in the gallbladder carcinoma specimens (0%, 0/8)." (PMID 36013219, 2022). "Here, we report novel somatic mutations of ERBB2 in gallbladder cancer, and its therapeutic implication in the presence and absence of KRAS (G12 V) and (G13D) mutations." (PMID 30304546, 2019). "KRAS mutations were identified in 3 (13%) intra-hepatic cholangiocarcinomas and 1 (33%) perihillar cholangiocarcinoma but were not identified in gallbladder carcinomas and extra-hepatic cholangiocarcinoma." (PMID 21303542, 2011). "suggests that KRAS G12V but not KRAS G13D mutations may prevent gallbladder cancer patients from responding to anti-EGFR therapy, KRAS G13D mutation as sensitive but G12V as resistant to anti-EGFR therapy." (PMID 40231011, 2024). "KRAS mutations were not identified in gallbladder carcinomas and extra-hepatic cholangiocarcinomas." (PMID 21303542, 2011).
renal cell carcinoma (28 papers, 2013 to 2025). "In accordance, high expression of BMP-1 was associated with EMT, angiogenesis, hypoxia pathway, KRAS signaling and shorter overall survival in renal cell carcinoma." (PMID 39792296, 2025). "This study characterizes the clinical and molecular features of KRAS-mutated Renal Cell Carcinoma (RCC), identifying three distinct subtypes, which arise from different cells of origin and exhibit diverse genomic alterations and metabolic profiles." (PMID 41375035, 2025). "Background/Objectives: KRAS mutations in renal cell carcinoma (RCC) are uncommon and most frequently described in papillary renal neoplasm with reverse polarity (PRNRP)." (PMID 41375035, 2025). "One case of renal cell carcinoma harbored a KRAS G12D variant and showed an oncocytic papillary phenotype." (PMID 36125633, 2023). "KRAS mutations in renal cell carcinoma (RCC) are rare, occurring in 1% of cases." (PMID 41375035, 2025). "This includes separating PRNRP into a biologically and clinically distinct entity from KRAS-mutant PRCC, and accordingly, developing tailored management strategies for each subtype within the evolving molecularly defined renal cell carcinomas." (PMID 41375035, 2025). "As for the regulated targets in the renal cell carcinoma pathway, TGFB1, EPAS1, HIF1A, VEGFA, KRAS, and PIK3CA regulated by miR-140 have been reported to interfere with KIRC." (PMID 35528546, 2022). "Furthermore, miR-134 is known as a tumor suppressor because it directly silences the KRAS oncogene as well as the integrin beta 1 (ITGB1) oncogene, the activity of which genes also promotes malignant transformation and proliferation of malignant cells, which can lead to renal cell carcinoma (RCC)." (PMID 33539381, 2021).
skin cancer (28 papers, 2012 to 2025). "In fact, it was recently reported that SOX2 and KRAS have interconnections, and that KRAS is mutated in 1.3% of skin cancers." (PMID 36899895, 2023). "The skin tumor was histologically identical to In‐N and exhibited mutations, including EZH1 Y642F, KRAS G60R, and TERT‐p C228T, which were also identified in In‐N." (PMID 41090246, 2025). "The KRAS G60R mutation was detected in In‐N (VAF 36.3%) and skin tumor (VAF 23.0%), while the TERT‐p C228T mutation was detected in In‐N (VAF 35.5%) and skin tumor (VAF 25.9%)." (PMID 41090246, 2025). "The skin tumor resembled STc of the primary TFND and harbored EZH1, KRAS and TERT promoter mutations." (PMID 41090246, 2025). "Molecular analysis revealed EZH1 mutations in both the Out‐N and STc of TFND, while KRAS and TERT promoter mutations were restricted to STc and the skin tumor." (PMID 41090246, 2025). "KRAS stands out as the predominant mutation in non-small cell lung cancer (NSCLC), while HRAS mutations are prevalent in skin cancer." (PMID 38247798, 2024). "To elucidate the role of N-WASP in skin cancer, we generated mice which expressed constitutively active KRas (KRasG12D) in keratinocytes with either homozygous (N-WASPKOG12D) or heterozygous (N-WASPHetG12D) N-WASP knockout upon Tamoxifen (TAM) injection." (PMID 37760426, 2023). "KRAS expression was also significantly correlated with clinical-pathologic features such as metastatic event and skin cancer." (PMID 27901498, 2017). "Based on these data, we reveal the role of the VEGF-C/VEGFR3-mediated KRAS/MAPK-YAP1/Slug pathway in skin cancer progression and propose that the VEGF-C/VEGFR3 axis is a promising target for the anti-VEGFR3 peptide." (PMID 27901498, 2017). "We further identify VEGF-C/VEGFR3-mediated YAP1 and Slug expression through KRAS/MAPK signaling in skin cancer." (PMID 27901498, 2017). "Our study confirms that VEGF-C is a critical inducer of cancer stemness, metastasis and invasion in skin cancer through regulating YAP1 expression via KRAS/MAPK signaling." (PMID 27901498, 2017). "In summary, our study reveals a novel mechanism by which the VEGF-C/VEGFR3 axis regulates Slug expression in skin cancer through the KRAS/MAPK-YAP1 pathway and contributes to the cancer stemness and metastasis of skin cancer." (PMID 27901498, 2017). "With this respect, all patients of our cohort with oncogenic alterations within the MAPK pathway (KRAS and NRAS) presented skin tumors at any time point during disease course, and the NRAS-mutated patient progressed from extensive tumor stage to systemic dissemination." (PMID 34771672, 2021). "Furthermore, expression of Slug was positively correlated with KRAS and MAPK1 expression in skin cancer." (PMID 27901498, 2017).
invasive carcinoma (27 papers, 2008 to 2025). A carcinoma that is not confined to the epithelium, and has spread to the surrounding stroma. "With regard to BRAF and KRAS mutation status in colonic precursor lesions and invasive carcinomas, wefound that KRAS-mutated HPP showed significantly higher Abi1 expression compared to healthy and inflamed mucosa as well as wild-type and BRAF-mutated HPP." (PMID 22808230, 2012). "Some authors suggest that within the pancreas, where KRAS mutation alone is insufficient to initiate an invasive carcinoma, the synergistic effect of microbe-induced inflammation and KRAS mutation could sustain the tumorigenic process." (PMID 34298645, 2021). "So, in all precursor lesions and invasive carcinomas, activating KRAS mutations led to a significant Abi1 overexpression against the background of the already existing upregulation in consequence of adenomatous change, perhaps related to enhanced PI3K/Akt signalling in these lesions." (PMID 22808230, 2012). "Given that KRAS mutations occur early in the multi-step progress towards invasive carcinoma, the cancer cell may have an initial interest in metabolic reprogramming for survival and mutational maintenance via prevention of catastrophic events; such as those mediated by reactive oxygen species." (PMID 25595905, 2015). "Although MBOTs rarely progress to invasive carcinoma, such progression appears to be driven by genomic events like mutant KRAS amplification and widespread copy number alterations." (PMID 40427213, 2025). "For comparison, KRAS and BRAF mutations are rarely detected in high-grade invasive carcinomas but are often present in borderline ovarian tumors, low-grade adenocarcinomas, and adjacent benign epithelium." (PMID 23344037, 2013). "In the majority of cases with KRAS or BRAF mutations, high c-MYC expression was consistently observed in lesions with low grade intraepithelial neoplasia to invasive carcinomas." (PMID 23045412, 2012). "KRAS mutations are an early mutagenic event in LUAD evolution, as demonstrated by multi-region sequencing that studied KRAS mutations in both minimally invasive adenocarcinoma and paired invasive carcinoma." (PMID 34831355, 2021).
mucinous ovarian cancer (27 papers, 2006 to 2025). An invasive malignant neoplasm that arises from the ovary and is characterized by the presence of malignant epithelial cells that contain intracytoplasmic mucin and may resemble the epithelial cells of the endocervix or gastrointestinal tract. "In ovarian mucinous tumors, cyclin dependent kinase inhibitor 2A (CDKN2A) and KRAS mutations represent the most common genetic alterations in both ovarian mucinous adenocarcinoma and their precursor lesions." (PMID 40936753, 2025). "KRAS mutations are frequent in mucinous ovarian tumors and occur in 40–50% of patients with mucinous ovarian cancer." (PMID 37185420, 2023). "If a Ras protein is inappropriately activated, as in the case of KRAS mutation in mucinous ovarian carcinoma, it can result in proteins that promote uncontrolled cell growth and proliferation." (PMID 36603894, 2023). "Another study demonstrated that this inhibitor exerts a synergistic effect by inhibiting mitogen-activated protein kinase (MEK) and PI3K in ovarian mucinous carcinoma cell lines with KRAS mutations." (PMID 34885229, 2021). "The frequency of KRAS mutation was particularly high in ovarian mucinous carcinoma, and KRAS mutation was associated with poor overall survival." (PMID 33936202, 2021). "In mucinous carcinoma of the ovary, previous studies clearly showed that the KRAS mutation was the important key point of the pathogenesis of the cancer." (PMID 31030485, 2019). "Nevertheless, the ovarian mucinous carcinoma patients with the KRAS mutation in our study showed excellent prognosis." (PMID 31030485, 2019). "KRAS gene mutations (>75%) appear to play a critical role in the etiology of mucinous ovarian cancer." (PMID 23344037, 2013). "The results from this study confirm previously demonstrated associations of KRAS mutations with well-differentiated and mucinous ovarian carcinomas." (PMID 23800114, 2013). "The KRAS mutation was the most commonly found mutation in mucinous ovarian cancer in this study." (PMID 31030485, 2019). "The high level of KRAS mutations in mucinous ovarian cancer may have treatment implications as targeted agents are being developed to target KRAS mutated tumors." (PMID 27231561, 2015). "Among OCa subtypes, KRAS mutations are frequently observed in borderline serous tumors, low-grade serous ovarian cancer (LGSOC), and mucinous ovarian cancer (MOC), with reported mutation frequencies ranging around 33–41%, 35–54%, and 57.1%, respectively." (PMID 41154625, 2025). "Mucinous ovarian carcinomas are associated with the copy number loss of CDKN2A and KRAS mutations, both of which are believed to be early events in tumorigenesis as they have been identified in benign and borderline mucinous precursor neoplasms." (PMID 37370967, 2023). "The biomakers for ovarian mucinous carcinoma, including the KRAS and HER2-neu genes, MEK, and PI3K, and molecular target drugs such as trastuzumab, lapatinib, and cetuximab have been gaining attention." (PMID 34885229, 2021).
mucinous ovarian cancer (continued). "The genetic mutation analysis found three mutations which were KRAS 27 cases (54%), PIK3CA 4 cases (8%) and BRAF 1 case (2%) The ovarian mucinous carcinoma patients with KRAS mutation in our study showed excellent prognosis." (PMID 31030485, 2019). "Overexpression/amplification of HER2 (ERBB2), a member of the epidermal growth factor receptor family that acts upstream of KRAS, has been identified in up to 35% of mucinous ovarian cancer cases." (PMID 27231561, 2015). "Mutations in KRAS and BRAF have been found to be common in low-grade serous and mucinous ovarian carcinomas." (PMID 17047655, 2006). "The suggestion is that blocking KRAS/BRAF signaling in mucinous ovarian carcinoma could potentially offer a more effective therapeutic approach." (PMID 38391958, 2024). "Molecular data on primitive mucinous ovarian carcinomas without the context of PMP showed frequent mutations in KRAS, without GNAS mutation." (PMID 34930348, 2021). "To study the association between recurrence and the KRAS mutation, we found that there was no recurrence and no disease related mortality in the KRAS mutated mucinous ovarian cancer patients." (PMID 31030485, 2019). "Similarly, mutations in CDKN2A and KRAS are commonly found in mucinous ovarian carcinomas as an early event in tumourigenesis, but are not required for diagnosis." (PMID 37370967, 2023). "Therapeutic agents targeting specific biomarkers and key molecular drivers of mucinous ovarian carcinoma such as ERBB2 and KRAS may exhibit promising results." (PMID 36603894, 2023).